USP26 (ubiquitin specific peptidase 26)
Diseases named in the same sentence as USP26 in open-access papers (continued):
Sharing a sentence is not in itself a finding about the gene and the disease.
virus infection (1 paper, 2024). "To ascertain the role of USP26 in virus infection in vivo, we infected wild-type (WT) and USP26-/- mice were infected via tail vein injection with EV71 and their survival monitored." (PMID 39058724, 2024). "Future research must investigate the role of USP26 in diverse viral infections." (PMID 39058724, 2024).
cancer (5 papers, 2015 to 2025). A tumor composed of atypical neoplastic, often pleomorphic cells that invade other tissues. "The data obtained in this study reveal that RAC1B effectively inhibits TGFβ1-dependent cell motility of mesenchymal subtype carcinoma cells by promoting protein expression of the inhibitory Smad, SMAD7, via intermittent transcriptional induction of the deubiquitinating enzyme, USP26." (PMID 32545415, 2020). "DUBs are critical key players in diverse processes such as (i) spermatogenesis (e.g. USP2, USP8, USP9y, USP14, USP26, Uchl-1, Uchl-3 and CYLD), (ii) cancer biology (e.g. USP7, USP10 and USP11), and (iii) stemness and differentiation (e.g. USP7, USP9x, USP22, USP44 and Psmd14)." (PMID 28659380, 2017). "Indeed, a plethora of cancer cell lines appear to have either lost (USP26 = 1457/USP37 = 446; COSMIC) or amplified (USP26 = 309/USP37 = 359; COSMIC) the expression of these DUBs." (PMID 26101254, 2015).
tumor (4 papers, 2020 to 2026). "Some, such as ubiquitin-specific protease 26 (USP26) and cylindromatosis, function as tumor suppressors, while others including USP13, OTU deubiquitinase 1, and USP18 promote oncogenesis." (PMID 41507147, 2026). "Several studies have suggested that expression of USP26 is not limited to germ cells, it is also expressed in somatic cells and tumor cells." (PMID 35397626, 2022). "The in vivo tumor growth assay showed that USP26 depletion significantly inhibited tumor growth in xenograft mice models." (PMID 35397626, 2022). "Consistently, in vivo tumorigenesis and metastasis assay suggested that USP26 functions as a promotor of tumor growth and metastasis." (PMID 35397626, 2022). "The in vivo tumor growth assay indicated that the tumor growth was significantly decreased in USP26 depletion cells, which effect could be further abrogated by TAZ overexpression." (PMID 35397626, 2022). "Our data are in line with those of Lui and coworkers who revealed for the first time the crucial role of USP26 in negative regulation of TGFβ signaling in MDA-MB-231 cells and cells from other tumor types." (PMID 32545415, 2020). "Given that USP26 mRNA was not changing between normal and tumor esophagus tissue but were increasing at the protein level, we hypothesized that USP26 is regulated by miRNA at the level of mRNA translation." (PMID 32760222, 2020).
infection (2 papers, 2017 to 2024). The state of being infected such as from the introduction of a foreign agent such as serum, vaccine, antigenic substance or organism. "It is plausible that USP26 plays a role in regulating the infection of other viruses." (PMID 39058724, 2024). "It was found that the expression of USP26 significantly increased at 8 hours post-infection." (PMID 39058724, 2024). "Furthermore, infection of ESCs with GFP-tagged mouse (m) USP26 led to ESC differentiation in an RA-independent manner." (PMID 28839133, 2017).
genetic disorders (1 paper, 2022). "Furthermore, we provided evidence that the amplification loop is of critical importance in human disease, because it is disrupted by RLIM and USP26 variants that cause human genetic disorders." (PMID 35857630, 2022).
USP26 also shares sentences with these, for which no sentence is quoted: anaplastic thyroid cancer (3 papers); esophageal cancer (2); androgen insensitivity syndrome (1); glioma (1); hearing loss (1); hypogonadism (1); lung carcinoma (1); oligospermia (1); pancreatic carcinoma (1); seminoma (1); stomach cancer (1).